CYP24A1 (cytochrome P450 family 24 subfamily A member 1)
Diseases named in the same sentence as CYP24A1 in open-access papers (continued):
Sharing a sentence is not in itself a finding about the gene and the disease.
melanoma (continued). "Reduced expression of CYP27B1 in primary melanomas was associated with shorter overall survival in one study, while expression of CYP24A1 was higher in naevi and early stage melanomas compared to normal skin, but decreased with melanoma progression in another." (PMID 25970336, 2015). "It has been shown before that induction of CYP24A1 expression by 1α,25(OH)2D3 treatment is more pronounced in responsive CRCs and melanomas in comparison to resistant ones." (PMID 26260259, 2015). "In a continuation of these studies, we have analysed changes in the expression of CYP24A1 during progression of melanocytic tumors and melanomas." (PMID 25334067, 2014). "In melanomas, the CYP24A1 level was negatively correlated with Brelow’s thickness, Clark’s level and the overall stage." (PMID 25334067, 2014). "To assess the role of CYP24A1 in melanoma biology, behavior and aggressiveness, we analyzed its expression in relation to histological type, proliferation rate, ulceration, tumor infiltrating lymphocytes (TILs), melaninization and solar elastosis." (PMID 25334067, 2014). "We found that the majority of melanoma lines had lower expression of the CYP24A1 gene than neonatal melanocytes (except 1 line) and adult melanocytes (except 3 lines)." (PMID 25334067, 2014). "Detailed analysis of CYP24A1 immunostaining in melanomas, stratified according to their Breslow’s thickness and Clark’s level, revealed comparable CYP24A1 levels in thin melanomas (Breslow < 2.0 mm and Clark I–II) and melanocytic nevi." (PMID 25334067, 2014). "With melanoma progression, CYP24A1 levels decreased and in advanced stages were comparable to the normal epidermis and metastases." (PMID 25334067, 2014). "The higher expression of CYP24A1 in strongly pigmented melanomas was a rather unexpected finding since our previous studies have shown a negative correlation between VDR and CYP27B1 expression." (PMID 25334067, 2014). "We found significant shortening of overall survival time (OS) for patients without CYP24A1 in primary melanomas (581 days vs. 1449 days for melanomas with low CYP24A1, and 2297 days for melanomas with high CYP24A1)." (PMID 25334067, 2014). "CYP24A1 was also analyzed in relation to lymph node and distant metastases and it was found that melanomas that developed metastases (pN1–3, pM1) had a distinct and significant decrease of CYP24A1 expression in comparison to non-metastasizing ones." (PMID 25334067, 2014). "The mean CYP24A1 immunostaining was also significantly higher in less advanced (pTis, pT1, pT2) than in more advanced (pT3, pT4) melanomas." (PMID 25334067, 2014). "In melanomas the CYP24A1 level was slightly elevated in comparison to the surrounding normal epidermis." (PMID 25334067, 2014). "In pTis and pT1–2 melanomas, high CYP24A1 immunostaining was more often observed than in pT3–4 melanomas (47.8% and 2.9%, respectively)." (PMID 25334067, 2014). "Advanced melanomas with a Breslow’s depth > 2.0 mm showed a more pronounced decrease of CYP24A1 than melanomas at III–V Clark levels." (PMID 25334067, 2014). "CYP24A1 was also reduced in melanomas with more aggressive phenotypes, as defined by high proliferative activity, ulceration and nodular type." (PMID 25334067, 2014). "In a separate experiment we tested the effect of induction of melanogenesis in SKMel-188 human melanoma cells on CYP24A1 gene expression." (PMID 25334067, 2014). "Higher CYP24A1 immunostaining was observed in superficial spreading melanomas (SSM) than nodular malignant melanomas (NMM)." (PMID 25334067, 2014). "Melanomas with high CYP24A1 immunostaining showed both the lowest mitotic index and the lowest percentage of Ki-67-positive melanoma cells." (PMID 25334067, 2014). "The expression of CYP24A1 was observed in 14.3% of normal skin samples, 80.0% of nevi, 61.4% of melanomas and 54.2% of metastases." (PMID 25334067, 2014).
melanoma (continued). "The incidence of cases with low CYP24A1 in nevi, melanomas and metastases was similar, 40.0%, 37.9% and 45.8% of cases, respectively." (PMID 25334067, 2014). "Correspondingly, the overall stage of melanomas was inversely correlated with the CYP24A1 immunostaining level (r = −0.5, p < 0.0001)." (PMID 25334067, 2014). "In conclusion, the local vitamin D endocrine system affects melanoma behavior and an elevated level of CYP24A1 appears to have an important impact on the formation of melanocytic nevi and melanomagenesis, or progression, at early stages of tumor development." (PMID 25334067, 2014). "The highest expression of CYP24A1 was seen in neonatal melanocytes and was statistically higher than in 12 melanoma lines, the exception being the YUAME (human melanoma from Yale Institute) line, and higher than in primary and immortalized keratinocytes." (PMID 25334067, 2014). "High CYP24A1 expression was observed mostly in nevi (40.0% of cases) with its incidence in malignant lesions being decreased (24.2% of primary melanomas and 8.3% of metastases)." (PMID 25334067, 2014). "To further analyze this surprising inverse correlation between CYP24A1 expression and melanoma progression, we compared CYP24A1 gene expression in cultured normal neonatal or adult epidermal melanocytes with 13 melanoma lines." (PMID 25334067, 2014). "We also found a positive correlation between melanin pigmentation and CYP24A1 expression (r = 0.3, p < 0.005), with significantly higher CYP24A1 in highly pigmented melanomas than in amelanotic or moderately pigmented tumors (p < 0.003)." (PMID 25334067, 2014). "Previously it has been reported that CYP24A1 mRNA was upregulated 7000 fold in the presence of 1,25D3 in several melanoma cell lines, concomitant with significant growth inhibition." (PMID 21283672, 2011). "In contrast, CYP24A1 mRNA induction was 100 times less in other melanoma cells impervious to 1,25D3 antiproliferative effects." (PMID 21283672, 2011). "Importantly, we also noticed the upregulation of the VDR and a slight downregulation of CYP24A1 protein level in melanoma cells simultaneously treated with 1,25(OH)2D3 and CPL304110 compared to monotreatment with the novel FGFRs inhibitor." (PMID 38473753, 2024). "CYP27A1, CYP27B1, and CYP2R1 are involved in the activation of vitamin D, whereas CYP24A1 and CYP3A4 are responsible for the degradation of the active vitamin D. CYP24A1, the primary catabolic enzyme of calcitriol, is overexpressed in melanoma tissues and cells." (PMID 38672780, 2024). "Several human malignancies, including melanoma, have been shown to have higher CYP24A1 levels." (PMID 38672780, 2024). "Similarly, CYP24A1 expression decreased with the progression of melanocytic tumor from nevi to primary melanomas to metastases." (PMID 38927967, 2024). "Also, there is no clear relationship between SNPs on vitamin D binding protein (VDBP), CYP27B1, and CYP24A1 and melanoma." (PMID 38927967, 2024). "The results of several studies have identified CYP24A1 expression in melanoma." (PMID 34208589, 2021). "Furthermore, the expression of vitamin D3-related genes was altered by vitamin D3 analogs, and the effects on the expression of VDR, RXR, PDIA3, CYP2R1 or CYP24A1 were stronger in WM98 melanoma cells in comparison to the A375 line." (PMID 30200275, 2018). "Interestingly, 20(OH)D produced by CYP11A1 can be hydroxylated by CYP24A1 to 20,24(OH)2D and 20,25(OH)2D, which are more potent in suppressing melanoma growth than calcitriol and 20(OH)D165." (PMID 29657326, 2018). "The finding of unexpected expression patterns of CYP24A1 in melanoma proposed that, in context of the dominant CYP11A1-driven alternative vitamin D metabolism pathway in the skin, CYP24A1 can produce biologically active tumor-suppressive vitamin D metabolites rather than degrading calcitriol." (PMID 29657326, 2018).
melanoma (continued). "CYP24A1, for example, is an enzyme that can metabolize vitamin D3 to generate biologically active hydroxyderivatives of 20(OH)D3, which possesses efficient anti-tumorigenic activities on melanoma cells." (PMID 28211524, 2017). "The role of CYP24A1 in tumor biology may be complex as indicated by clinicopathological studies on patients with melanoma." (PMID 26260259, 2015). "The statistically highest mean CYP24A1 level was found in nevi and early stage melanomas." (PMID 25334067, 2014). "However, changes in CYP24A1 in relation to melanin content are consistent with a regulatory function of melanogenesis or its intermediates on biological properties of melanoma cells." (PMID 25334067, 2014). "Thus, CYP24A1 expression in normal epidermis was lower than in melanocytic nevi and early-stage melanomas (pTis–pT2), while being similar to pT > 2 and metastatic melanomas." (PMID 25334067, 2014). "Studies examining associations of polymorphisms in genes coding for vitamin D metabolism-related proteins (1α-hydroxylase [CYP27B1], 1,25(OH)2D-24hydroxylase [CYP24A1], vitamin D-binding protein [VDBP]) and cancer risk are scarce, especially with respect to melanoma." (PMID 22576141, 2012). "Additional research investigates vitamin D’s role in cancer prevention, specifically analyzing VDR, CYP27B1, CYP24A1, and ROR expression in the human uveal tract and melanoma." (PMID 40334012, 2025). "CYP11A1, CYP24A1, CYP27B1, CYP2R1, and CYP3A4 are expressed in WM98 and A375 human melanoma cell lines." (PMID 38672780, 2024). "It has to be underlined that this analog, also showed high potency against two other melanoma cell lines in the study (A375 and WM98) and minimal stimulation of CYP24A1." (PMID 30200275, 2018). "Post-treatment of A375 melanoma with 1,25(OH)2D3, expression of VDR was inhibited slightly, while CYP24A1, the vitamin D catabolic enzyme, was strongly induced." (PMID 26760999, 2016). "A similar finding has been reported from studies of murine melanoma cell lines, in which pigmentation increased the expression of VDR and CYP24A1 at the mRNA level, and of SK-MEL 188 human melanoma cells." (PMID 26760999, 2016). "This is consistent with our previous observation showing the reduction of OS and DFS of patients with a pigmented melanomas at stage 3 and 4, and on expression of several vitamin D related pathways such as VDR, CYP24A1 and CYP27B1 and HIF-1α." (PMID 27542227, 2016). "The major CYP11A1-derived hydroxyderivatives can also be metabolized by CYP24A1, which catalyzes their hydroxylation at C24 or C25, and can increase their potency rather than decrease it, at least for inhibition of melanoma cell proliferation." (PMID 38927967, 2024). "On the other hand, the expression of VDR and its splicing variants and other vitamin D related genes (RXR, PDIA3, CYP3A4, CYP2R1, CYP27B1, CYP24A1 and CYP11A1) was detected in WM98 and A375 melanomas with the transcript levels being modulated by vitamin D analogs." (PMID 30200275, 2018). "This secosteroid could be of great value for the treatment of melanomas which display decreased expression of the VDR and enhanced expression of CYP24A1." (PMID 25811927, 2015). "Furthermore, pigmented B16 melanoma cells show attenuation of responsiveness to ligand stimulation of VDR translocation to nucleus, and expression of VDR and CYP24A1 genes, indicating that VDR signaling is malfunctioning in melanotic cells." (PMID 25811927, 2015). "Administration of 1 μM 1,25(OH)2D3 to B16-F10 cells increased VDR and CYP24A1 mRNA levels in both pigmented and non-pigmented melanoma cells." (PMID 25811927, 2015). "CYP11A1 is also expressed in normal melanocytes and melanoma cells, so these cells can potentially carry out the CYP11A1-initiated pathways of vitamin D metabolism, with subsequent modification of products by CYP27B1, CYP24A1, or CYP27A1, which are also expressed in melanoma cells." (PMID 38927967, 2024).
melanoma (continued). "Thus, genes controlling the turnover of vitamin D (CYP27B1, CYP24A1), vitamin A (ALDH1A3, AKR1B10), and cholesterol (CYP7B1), were up-regulated in psoriasis, whereas melanomas showed downregulation of genes regulating turnover of vitamin A (AKR1C3), and cholesterol (CYP39A1)." (PMID 26901218, 2016). "Furthermore, incubation of human malignant melanoma SK-MEL 188b cells with active form of vitamin D3 did not lead to the appearance mRNAs for either VDR or CYP24A1." (PMID 26760999, 2016). "The lack of stimulation of CYP24A1 expression in murine B16-F10 melanoma cells by 21(OH)pD may be explained by the impaired interaction with the VDR." (PMID 25811927, 2015). "Similarly, disease-free survival time (DFS) was the highest in melanomas with high CYP24A1 in comparison to melanomas with low or absent CYP24A1 (1607, 539, 459 median days, respectively)." (PMID 25334067, 2014). "Furthermore, the clinical outcome correlated well with pathology, e.g., OS in CYP24A1-negative melanomas was significantly shorter in comparison to melanoma expressing high CYP24A1, and DFS was positively correlated with higher expression of CYP24A1." (PMID 25334067, 2014). "However, for melanoma progression evaluated both with Breslow’s thickness and Clark’s level, negative correlation was found for CYP24A1 immunostaining (r = −0.3; p = 0.011 and r = −0.3; p = 0.02, respectively)." (PMID 25334067, 2014). "However, expression of the CYP24A1 gene in immortalized HaCaT keratinocytes was lower than in the YUAME line, at a similar level to expression in the YUKIM line and higher than in the other 11 melanoma lines examined." (PMID 25334067, 2014). "Similarly, melanomas without necrosis also showed significantly higher CYP24A1 immunostaining in comparison to melanomas with necrosis." (PMID 25334067, 2014). "Also, the lack of CYP24A1 expression in melanomas was accompanied by a higher proliferation rate and unfavorable prognostic histopathological markers (ulceration, necrosis, nodular type melanoma)." (PMID 25334067, 2014). "In addition, melanomas with lymph node and distant metastases also had significantly lower CYP24A1 levels than non-metastasizing melanomas." (PMID 25334067, 2014). "In addition, the expression of the enzyme-activating vitamin D (CYP27B1) was inversely related to melanin in melanoma cells in vivo and melanoma cells cultured in vitro, while the expression of CYP24A1 was lower in non-pigmented melanomas vs. highly melanized ones." (PMID 35359389, 2022). "Importantly, higher CYP24A1 expression was found in non-ulcerated melanomas." (PMID 25334067, 2014). "Furthermore, shorter OS and DFS were found in melanomas without detectable CYP24A1." (PMID 25334067, 2014).
colon carcinoma (22 papers, 2005 to 2023). "The frequency of the gene polymorphism of CYP24A1 associated with colon cancer is relatively constant among the various population in the world (Europe and China)." (PMID 34191826, 2021). "One such study explored the association between CYP24A1 polymorphisms and risk of colonic polyps, colon cancer, and colitis in 144 subjects with colonic polyps, 96 subjects with colon cancer, and 44 subjects with UC." (PMID 32422882, 2020). "Multiple copies of the gene have been detected in colon cancer, thus, CYP24A1 has been proposed to be a tumor suppressor." (PMID 37047477, 2023). "Since previous researches confirmed enhanced activity of CYP24A1 in less differentiated colon cancer cells, it would be expectable to find increased concentrations of 24,25(OH)2D3 in systemic circulation of CRC patients." (PMID 33269020, 2020). "We established xenografts in male SCID mice using a colon cancer cell line stably overexpressing CYP24A1." (PMID 26238339, 2016). "We transfected the colon cancer cell line HT29 either with GFP‐tagged CYP24A1 or an empty vector containing only GFP." (PMID 26238339, 2016). "The change is predicted to damage the function of the enzyme by both Polyphen and SIFT, and analysis of over-expressed mutant protein in colon cancer cells HCT116 demonstrated decreased CYP24A1 and increased intracellular levels of 1,25(OH)2D3." (PMID 24562971, 2014). "In undifferentiated colon cancer cells CYP24A1 (a key enzyme in vitamin D metabolism) expression was increased compared with normal cells, so it potentially prevented the synthesis of 1,25-dihydroxyvitamin D3 and restricted its cancer protective effects." (PMID 22284859, 2012). "Through the case-only study of genotype-phenotype analysis, CYP24A1 polymorphism rs6068816 AX was significantly associated with colon cancer (P = 0.03, OR = 2.08, 95%CI: 1.10–3.96), not rectal cancer." (PMID 34191826, 2021). "This suggests that targeted inhibition of CYP24A1 could be used as a possible additional therapy for colon cancer patients with tumours overexpressing CYP24A1, whereas high dietary vitamin D3 in combination with soy could be beneficial for prevention." (PMID 26238339, 2016). "In colonic carcinomas, a positive correlation between CYP24A1 expression and Ki-67 was reported." (PMID 25334067, 2014). "As 1,25-(OH)2D3 induces CYP24A1 in colon carcinoma cells, this could explain, at least in part, the parallel rise of the vitamin D catabolic enzyme during tumor progression to low grade malignancy." (PMID 24213465, 2012). "CYP24A1 is particular interesting as it is the major enzyme of the degradation pathway that showed a 97-fold increase after vitamin D treatment of rats or 12-fold increase in a human colon cancer cell line." (PMID 15651992, 2005). "Interestingly, however, the induction of CYP24A1 by the inhibition of epigenetic changes in colon cancer could be an indirect effect via regulation of genes operating upstream of CYP24A1 suggesting the complexity of epigenetic regulation of CYP24A1 expression in cancer." (PMID 29657326, 2018). "From these data we speculate that up-regulation of CYP24A1 in the tumor is uncoupled from VDR, and therefore is independent of the local levels of 1,25(OH)2D3, as it has been suggested for benign and malignant tumors of the colon." (PMID 25090635, 2014). "The amplification of CYP24A1 was identified only in malignant, but not benign colon tumors, thus these observations suggest that CYP24A1 overexpression and inactivation of calcitriol may be a key feature of tumor cells." (PMID 34208589, 2021).